IL33 (interleukin 33)
Diseases named in the same sentence as IL33 in open-access papers (continued):
Sharing a sentence is not in itself a finding about the gene and the disease.
liver disease (continued). "Moreover, we also hope to expand the study of IL-33 to more liver diseases and find more potential therapeutic applications of IL-33." (PMID 29180837, 2017). "Hence, more studies are required to fully understand the role of IL-33 in the regulation of liver disease and its signalling pathways and regulatory networks." (PMID 29180837, 2017). "In this review, we will focus on the roles of IL-1, IL-18, and IL-33 in various liver diseases, following a brief introduction to the IL-1 family, with the aim of clarifying the molecular and cellular networks involving each cytokine that are activated in liver diseases." (PMID 26549942, 2015). "No change could be observed in children plasma IL-33 levels when liver disease was present or not arguing against the association of liver disease with IL-33 in our cohort." (PMID 31849991, 2019). "However, further studies are required to elucidate whether targeting of the IL-33/ST2 axis might be a novel therapeutic strategy for treatment of sterile inflammation-related liver disease." (PMID 30213101, 2018). "Elevated IL-33 levels have been described in patients with acute and chronic liver disease, including AIH, suggesting that IL-33 contributes to liver disease pathology." (PMID 38571949, 2024). "We have already known IL-33/ST2 axis participates in the pathogenesis of various diseases, including liver diseases, renal diseases, and neurological diseases." (PMID 32908451, 2020). "The Interleukin-33 (IL-33)/ST2 receptor signaling axis has been demonstrated to be involved in several autoimmune and liver diseases." (PMID 31632941, 2019). "IL-33 concentration was lower among patients with a METAVIR fibrosis score F1-F2, compared with those having a more advanced liver disease (METAVIR stage F3-F4)." (PMID 23423835, 2012). "As of yet, our attempt to define the clinical value of IL-33 in monitoring schistosomiasis-driven liver disease in school children from a polyparasitic site does not support the use of this clinical parameter." (PMID 31849991, 2019). "Intriguingly, plasma IL-33 levels in S. mansoni-infected participants without liver disease were apparently lower than levels of plasma IL-33 in controls but did not achieve statistical significance." (PMID 31849991, 2019). "Moreover, we demonstrated that IL-33 has an inhibitory effect on IL-25-mediated IL-17A expression in hepatic ILC2, indicating that in IL-33-triggered liver diseases, the development of inflammatory ILC2 might be suppressed." (PMID 31974518, 2020). "No recent studies have solely focused on the role of IL-33 in liver diseases affecting patients." (PMID 32486265, 2020). "Thus, IL-6 plays an important role in the pathology of liver diseases and ILC2 might contribute to IL-6-mediated hepatic immune regulation following activation by IL-33." (PMID 31974518, 2020). "Notably, however, though the plasma levels of IL-33 in S. mansoni-infected participants with liver disease was not different to those without liver disease, these levels were lower than those of the egg-negative control groups." (PMID 31849991, 2019). "Indeed, liver transcripts of IL-33 were overexpressed in our NASH model, but IL-33 deficiency did not improve the liver disease." (PMID 28611297, 2017). "In humans, the relevance of the IL-33/ST2 pathway to liver pathophysiology has been documented in liver failure, alcoholic hepatitis, and nonalcoholic steatohepatitis, suggesting a pivotal role of IL-33 in inflammatory liver diseases, but its role in LT has not been established yet." (PMID 34621275, 2021).
Cognitive impairment (27 papers, 2017 to 2025). Abnormal cognition is characterized by deficits in thinking, reasoning, or remembering. "Overall, these findings demonstrate that IL-33 deficiency exacerbates cognitive deficits and promotes chronic neuroinflammatory responses following rmTBI." (PMID 40764944, 2025). "Our study suggests that IL-33 is a novel target for improving spatial and recognition memory-associated cognitive deficits in D-gal–administered mice." (PMID 39224568, 2024). "The precise IL-33 effect on cognition regulation in disease and healthy conditions is critical for regulating age-associated cognitive impairment and synaptic plasticity." (PMID 37892176, 2023). "The association of IL-33 with cognitive impairment was also demonstrated in studies of patients and animal models of neuroinflammation-related diseases." (PMID 35974336, 2022). "We showed that ST2-deficient mice were resistant to PbA-induced neuropathology and demonstrated a deleterious role of CNS endogenous IL-33 in the neuropathogenesis associated with cognitive disorders." (PMID 32917228, 2020). "Our results reveal that after PbA-infection, the microglial production of IL-1β which affects neurogenesis and causes cognitive impairments, is mediated by IL-33/ST2 pathway, prior to the apparition of ECM-induced clinical neurological symptoms." (PMID 28448579, 2017). "We next assessed the potential implication of IL-33/ST2 pathway in the cognitive impairment associated with PbA-infection and ECM development." (PMID 28448579, 2017). "Given that the ST2 receptor is predominantly expressed in microglia, we then focused on microglia and found that IL-33 deficiency reduced microglial phagocytic activity and impaired their ability to clear pathological proteins, thereby exacerbating cognitive impairment after rmTBI." (PMID 40764944, 2025). "IL-33 has also been implicated in cognitive impairment and dementia." (PMID 39224568, 2024). "Reams of previous studies have shown that IL-33 has both pro- and anti-inflammatory effects, playing dual roles in the progression of diseases linked to cognitive impairment by regulating the activation and polarization of immune cells, apoptosis, and synaptic plasticity." (PMID 35974336, 2022). "Given the importance of microglia in the neurotoxic or neuroprotective inflammatory responses, CNS IL-33 may be a key factor in the neuroinflammatory processes and associated with cognitive impairments." (PMID 32917228, 2020). "Finally, we demonstrated that IL-1αβ deficient mice were resistant to cognitive disorders after intra-hippocampal IL-33 injection." (PMID 32917228, 2020). "Thus, hippocampal IL-33 induced an inflammatory state, including IL-1β overexpression by microglia cells, being causative of the cognitive impairment." (PMID 32917228, 2020). "Interleukin (IL)-33 is expressed in a healthy brain and plays a pivotal role in several neuropathologies, as protective or contributing to the development of cerebral diseases associated with cognitive impairments." (PMID 32917228, 2020). "In this study, we hypothesized that IL-33 may contribute to the cognitive defects associated with experimental cerebral malaria." (PMID 28448579, 2017). "Thus, IL-33 treatment attenuated the severity of brain injury caused by dysregulated inflammation and may mitigate cognitive impairment after focal cerebral ischemia." (PMID 35974336, 2022). "In contrast, sST2 competitively binds to IL-33 and mitigates neuroprotective effects, and studies have shown that high levels of sST2 demonstrated mild cognitive impairment and AD." (PMID 39925809, 2025). "Mouse models of AD have shown that IL-33/IL1RL1 signaling can alleviate cognitive impairment in AD by activating microglia to phagocytize amyloid beta." (PMID 40725187, 2025). "In patients, serum and CSF IL-33 and IL-10 levels were significantly reduced in AD and mild cognitive impairment (MCI), whereas IL-1β levels were increased." (PMID 39071802, 2024).
Cognitive impairment (continued). "IL-33 has been found to have opposite effects in the progression of diseases leading to cognitive impairment." (PMID 37759873, 2023). "A clinical study has shown that IL-33 was significantly reduced in cerebrospinal fluid and serum of AD and mild cognitive impairment patients." (PMID 36138980, 2022). "Conversely, bilateral intrahippocampal injection of IL-33 (400 ng) induced IL-1β overexpression by microglia cells and cognitive impairment in mice." (PMID 36138980, 2022). "Our study showed that surgery/anesthesia induced postoperative cognitive impairment accompanied by decreased astrocyte-derived IL-33 in aged mice." (PMID 36138980, 2022). "In AD mouse and RNS rat models, IL-33 has been proven to improve cognitive defects via anti-inflammation." (PMID 36138980, 2022). "As the main inflammatory cells in the CNS, microglia and astrocytes secrete several pro-inflammatory factors, such as IL-33, TNF-α, IL-1β, IL-18, IL-6, ROS, and NO, leading to neuroinflammation, which is thought to be associated with cognitive impairment." (PMID 35974336, 2022). "The link between plasma sST2 and tau in this study, along with the associations with cognitive impairment in this population, and similar findings in an ECM model with IL-33 upregulation, suggest a connection between the ST2/IL-33 pathway and neuronal damage." (PMID 35800259, 2022). "Studies support a role for endogenous IL-33 in increasing inflammation and contributing to development of ECM and associated cognitive impairments." (PMID 35800259, 2022). "Specifically, patients with AD and mild cognitive impairment exhibit reduced gene expression of IL33 and increased serum levels of soluble ST2 (the decoy receptor of IL-33), respectively." (PMID 33847763, 2021). "This rescue of the IL-33-induced phenotype suggests that the cognitive impairments induced by IL-33 involved a neuroinflammatory process." (PMID 32917228, 2020). "We previously proposed a role for IL-33/ST2 signaling pathway in the hippocampus in the cognitive impairments after PbA-infection, especially on the memory process." (PMID 32917228, 2020). "Minocycline administration through its anti-inflammatory activity attenuated the microglia activation of IL-33 treated mice, in line with previous reports in cognitive disorders." (PMID 32917228, 2020). "Here we focused on the implication of the endogenous IL-33/ST2 pathway in ECM-associated CNS and cognitive defects." (PMID 28448579, 2017). "In addition, astrocytic Ca2+ activity, connexin 30 and 43 levels, and IL-33 signaling are all impaired in AD, and restoration of IL-33 function has been shown to reverse cognitive deficits." (PMID 40723783, 2025). "Furthermore, we designed a therapeutic strategy targeting the IL-33/ST2 axis to alleviate cognitive impairment in rmTBI mice." (PMID 40764944, 2025). "Mice without IL-33 develop AD, which is characterized by tau abnormalities and significant neuronal loss in the hippocampus and accelerated aging, memory or cognitive impairment, and cerebral cortex." (PMID 39925809, 2025). "IL-33 treatment could reduce the accumulation of Aβ plaques, neuroinflammation, and cognitive impairment in AD mouse models." (PMID 37175665, 2023). "They found that IL-33/ST2 signaling was significantly downregulated in the brains of patients with AD and in mouse models and that this was associated with increased neuroinflammation and cognitive impairment." (PMID 37175665, 2023). "Furthermore, treatment with IL-33 or its agonist reduced neuroinflammation, improved synaptic plasticity, and alleviated cognitive impairment in the AD mouse model of AD." (PMID 37175665, 2023). "This article will summarize the current findings on the effects IL-33 exerts on cognitive function by regulating neuroinflammation, and attempt to explore possible therapeutic strategies for cognitive disorders based on the adverse and protective mechanisms of IL-33." (PMID 35974336, 2022).
Cognitive impairment (continued). "IL-33 may therefore have a protective effect against aging-induced cognitive impairment by promoting the phagocytotic activity of microglia." (PMID 35974336, 2022). "Instead, the role of IL-33/sST2 in cognitive impairment may be greater in older children with less neural plasticity." (PMID 35800259, 2022). "We then hypothesized that the cognitive impairment induced by exogenous IL-33 may be mediated in part by microglia derived IL-1." (PMID 32917228, 2020). "Based on our in vivo and in vitro results, we propose a CNS amplification loop between IL-1β and IL-33 produced by microglia and oligodendrocyte respectively, which may contribute to the early cognitive defects before ECM development." (PMID 28448579, 2017). "Here, we tested the hypothesis that IL-33, an alarmin with multiple functions which is highly expressed in the brain, may contribute to ECM-associated cognitive defects." (PMID 28448579, 2017). "In this review, we sum up that IL-33 and other pro‐inflammatory mediators may form autocrine and paracrine amplification loops between astrocytes and other immune cells, further exacerbating CNS inflammation and leading to cognitive impairment." (PMID 35974336, 2022). "Similarly, plasma sST2 and the activity it represents in the ST2/IL-33 pathway, may be more important in the pathways leading to cognitive impairment in children ≥ 5 years of age." (PMID 35800259, 2022). "Additionally, in a murine model of ECM, IL-33 induced the release of Th2 cytokines IL-4, IL-5, and IL-13, as well as the expansion of Tregs, while suppressing the pro-inflammatory response, which alleviated cognitive impairment and prevented ECM development." (PMID 35974336, 2022). "Similarly, recombinant IL-33 was also observed to significantly reduce the nuclear translocation of NF-κB and disrupt its downstream pro-inflammatory mechanisms in monocytes derived from patients with AD and mild cognitive impairment (MCI) in vitro." (PMID 35974336, 2022). "Thus, the amplification loop between IL-1β and IL-33 in the CNS may contribute to plasmodium-induced cognitive deficits." (PMID 35974336, 2022). "Thus, we suggest that in neuropathological conditions IL-33 released by astrocytes and/or oligodendrocytes may activate microglia and induce IL-1-dependent cognitive defects." (PMID 32917228, 2020). "Thus, IL-1β-producing microglia are required for IL-33 neurotoxic effects on cognitive impairment." (PMID 32917228, 2020). "Therefore, the short memory impairment seen on day 5 post-PbA infection in WT mice was absent in ST2 deficient mice, indicating that the IL-33/ST2 pathway is involved in the cognitive defects seen at this early stage of ECM development." (PMID 28448579, 2017). "In response to inflammatory stimuli, including IL-33 through ST2 pathway, microglial cells released IL-1β which in turn activated oligodendrocytes to produce high levels of IL-33, documenting a CNS endogenous IL-33 inflammatory loop that may contribute to PbA induced cognitive disorders." (PMID 28448579, 2017). "Similar to the effect of IL-33 injection that reversed cognitive deficits in APP/PS1 mice, MS1262 inhibition of G9a upregulated IL-33 expression." (PMID 38045363, 2023). "Thus, the IL-33/ST2 signaling pathway may contribute to the cognitive impairment typical of neurological diseases at least in part by promoting the proliferation, recruitment, and activation of astrocytes and microglia, which release pro-inflammatory cytokines." (PMID 35974336, 2022). "Also, by restoring type 2 signaling through therapeutic injection of IL-33, IL-4 or IL-13, or augmenting hippocampal IL-4 with phosphatidyl serine, neurosynaptic function might be preventatively enhanced or bolstered in mild cognitive impairment or in early AD." (PMID 39071802, 2024). "PbA-infection-induced early short-term and spatial memory defects in wild-type mice, which was proportional to the IL-33 level, while ST2-deficient mice did not develop a cognitive deficit." (PMID 35974336, 2022).
Cognitive impairment (continued). "The IL-33/ST2 signaling pathway participates in a complex network of multicellular interactions between the immune and nervous systems in the CNS and is also central for infection-induced cognitive impairments." (PMID 35974336, 2022). "Thus, IL-33/ST2 signaling may mitigate TBI- and ICH-induced cognitive impairments through the inhibition of ERS, autophagy, and apoptosis." (PMID 35974336, 2022). "The available studies in these disease models have demonstrated that IL-33/ST2 pathway might inhibit the inflammatory response and reduce cognitive impairment by promoting the polarization of microglia toward the anti-inflammatory M2 phenotype, which may be a reliable therapeutic strategy." (PMID 35974336, 2022). "Here, the significant reduction of neuroblast proliferation in PbA-infected WT mice was prevented in the absence of IL-33/ST2 pathway, which, in line with the absence of cognitive defect in these mice, confirms a causality link between neurogenesis and cognitive defects." (PMID 28448579, 2017). "In the brains of human patients and AD model mice, IL-33 and ST2 are respectively highly expressed in astrocytes in close proximity to APs and NFTs, whereby IL-33 may exacerbate the release of pro-inflammatory molecules from astrocytes and contribute to Aβ-induced cognitive deficits." (PMID 35974336, 2022). "Another human study reported that when compared with the mild cognitive impairment (MCI) patients with subsequent AD conversion, the MCI patients without AD conversion had higher levels of IL-33+ cells that were also positively correlated with hippocampus volumes." (PMID 32678011, 2020).
coronary artery disease (26 papers, 2013 to 2025). "In conclusion, our results showed that the higher serum concentrations of IL-33 were associated with ischemic heart disease." (PMID 34754275, 2021). "In patients with both stable and unstable coronary artery disease, an increase of IL-33 serum levels after stent implantation is associated with a higher rate of in-stent restenosis." (PMID 24725541, 2014). "We investigated an association of soluble ST2 (sST2) and IL-33 serum levels with different clinical stages of coronary artery disease." (PMID 24751794, 2014). "The increasing levels of IL-33 and ST2 are also found after physical exercise in normal people or those with ischemic heart disease; these findings suggest that exercise-induced IL-33/ST2 maybe associated with astrocyte-microglia crosstalk." (PMID 34631212, 2021). "The IL-33/ST2 signaling pathway plays an important role in coronary artery disease (CHD); however, few studies have explored how variants in IL-33/ST2 genes influence CHD risk." (PMID 25517029, 2014). "The IL-33/ST2 axis is reported to be controversially associated with coronary artery disease (CAD)." (PMID 36337880, 2022). "Both inflammatory host response and comorbidities such as heart failure (HF) and coronary artery disease (CAD) revealed augmented expressions of interleukin (IL)-33 and soluble suppression of tumorigenicity 2 (sST2)." (PMID 35011794, 2021). "The aim of this study was to determine the gene expression and protein levels of interleukin‐33 (IL‐33), fetuin A and cytokeratin 18 (CK‐18) in the pericardial fluid (PF) and plasma of patients with coronary artery disease (CAD) undergoing coronary artery bypass grafting (CABG)." (PMID 40437664, 2025). "The role of IL-33/ST2 signaling pathway in ischemic heart disease has been highlighted." (PMID 24335613, 2013). "The effect of interleukin 33 (IL-33) in the inflammatory process generates significant interest in the potential significance of IL-33 as a biomarker for coronary artery disease (CAD)." (PMID 28045954, 2017). "IL-33 levels were not different between the patients with stable coronary artery disease and acute coronary syndrome and the control group." (PMID 24751794, 2014).